PRL (prolactin)
Diseases named in the same sentence as PRL in open-access papers (continued):
Sharing a sentence is not in itself a finding about the gene and the disease.
hyperprolactinemia (continued). "One clinically important question is also the effect of the endometriosis treatment on the prolactin serum levels as well as the question of whether the medical treatment of hyperprolactinaemia could be useful in improving endometriosis and fertility in endometriosis patients." (PMID 39407928, 2024). "Thus, PRL excess as in hyperprolactinaemia may induce the development and progression of MetS by different mechanistic pathways." (PMID 39663784, 2024). "Additionally, the oral administration of HY7801 (109 colony-forming units/kg/day) to mice with metoclopramide-induced hyperprolactinemia reduced uterine tissue mass and endometrial thickness, both of which were increased excessively in the presence of prolactin." (PMID 39599674, 2024). "Low PRL concentration in relation to adenoma diameter may be a manifestation of low tumor differentiation or the result of the hook effect, especially in tumors ≥ 3 cm with normal concentrations or mild hyperprolactinemia ≤ 200 ng/mL in laboratory findings." (PMID 38370355, 2024). "However, there is increasing evidence of metabolic alterations in patients with hyperprolactinemia, which might be related to the increased cardiovascular morbidity observed in patients with high prolactin levels." (PMID 38645431, 2024). "Moreover, prolactin levels > 500 ng/mL were highly suggestive of macroprolactinomas, although they were also found in very few patients (<2%) with microprolactinomas or drug-induced hyperprolactinemia." (PMID 39420933, 2024). "Furthermore, prolactin levels > 500 ng/mL were almost exclusively found in patients with prolactinomas but also in < 2% of the patients with microprolactinomas or drug-induced hyperprolactinemia." (PMID 39420933, 2024). "From our literature searches, five articles were included in this umbrella review, and these meta-analyses reported that aripiprazole, metformin and dopamine agonists may be effective at reducing prolactin concentrations in patients with antipsychotic-induced hyperprolactinemia." (PMID 38505795, 2024). "Although prolactin itself is not considered a direct cause of PG, hyperprolactinemia might contribute to the development of gynecomastia by causing secondary hypogonadism." (PMID 39797240, 2024). "To challenge this idea, we first examined whether the treatment with SCH23390 and quinpirole mitigated hyperglycemia, hyperinsulinemia, and hyperprolactinemia in Trappc9-KO mice, as dopamine transmission modulates glucose homeostasis and inhibits prolactin and insulin secretion." (PMID 38889014, 2024). "Thus, the present study investigated whether coexisting euthyroid Hashimoto thyroiditis modulates the impact of chronic metformin treatment on plasma prolactin levels in middle-aged and elderly men with antipsychotic-induced hyperprolactinemia." (PMID 39204081, 2024). "If hyperprolactinemia recurs after treatment suspension, a second attempt to withdraw the dopamine agonist may be undertaken after 2 more years of treatment, provided that normal prolactin levels are maintained." (PMID 38578473, 2024). "Therefore, the predominance of macroprolactin, which is the main molecular form of PRL in the serum of patients with a normal concentration of monomeric PRL, is associated with no symptoms or a mild course of hyperprolactinemia." (PMID 38396659, 2024). "Immediately following the transsphenoidal surgery for lactotroph PitNET with the rapid normalization of hyperprolactinemia state, prolactin inhibiting factor might be present in relatively high concentrations, resulting in excessive suppression of prolactin secretion." (PMID 39080760, 2024). "Moreover, females with tubal factor infertility also present more commonly with abnormal prolactin concentration, suggesting that hyperprolactinemia may further decrease fertility potential in this category of patients." (PMID 36678618, 2023).
hyperprolactinemia (continued). "In addition, patients with GH–PRL PitNET, as could be expected, have additional hyperprolactinemia-induced symptoms, such as decreased libido and menstrual cycle alterations." (PMID 37762304, 2023). "It was demonstrated that the short luteal phase precedes the full clinical picture of hyperprolactinemia, suggesting that luteal phase insufficiency may be the first sign accompanying an increase in prolactin levels or the consequence of less severe hyperprolactinemia." (PMID 36678618, 2023). "Correlations between prolactin levels and the assessed biomarkers suggest that this risk may be greatest in individuals with severe hyperprolactinemia, not included in the present study." (PMID 37176648, 2023). "Besides various hypotheses concerning the mechanism responsible for high levels of PRL in COVID-19 patients, it is postulated that stress accompanying COVID-19 may induce hyperprolactinemia." (PMID 36833950, 2023). "However, significantly lower fertilization rates were found in patients with prolactin < 10 μg/L compared with patients with hyperprolactinemia and lower cleavage rates were achieved in the low prolactin group in contrast with women with normal or elevated serum concentrations." (PMID 36678618, 2023). "For this reason, in patients with hyperprolactinaemia administered with DAs it might be useful to aim for PRL levels within the normal range to avoid a possible unfavorable metabolic effect due to excessively low PRL." (PMID 36237192, 2022). "Therefore, determining a baseline level of prolactin before starting an anti-psychotic drug may help clinicians to determine if hyperprolactinemia is actually induced by the medications." (PMID 35223307, 2022). "A third limitation is the different methods employed by various studies for the assessment of serum concentration of PRL; and the absence of a comprehensive explanation for the exclusion methods of hyperprolactinemia pathologic causes in the majority of included studies." (PMID 36552931, 2022). "Indeed, pregnancy represents a model of prolonged exposure to hyperprolactinemia that allows studying mechanisms through which PRL could affect gluco-insulinemic metabolism." (PMID 36237192, 2022). "In addition, the symptomatic state of excess PRL that could be developed via hypothalamic-pituitary axis disorders or drugs -referred to as pathologic hyperprolactinemia- increases post-prandial insulin resistance." (PMID 36471299, 2022). "Similarly, aripiprazole exhibited the strongest association with decreased PRL content in blood, indicating that its use may protect patients taking OLZ from hyperprolactinemia." (PMID 36313772, 2022). "In addition, since thyrotropin-releasing hormone (TRH) acts as a stimulating factor for PRL, prolonged primary hypothyroidism may result in a stimulus on the hypothalamic–pituitary–thyroid axis with consequent hyperprolactinemia." (PMID 34207687, 2021). "Aripiprazole or other prolactin-sparing atypical APDs like cariprazine may be an alternative treatment option or be considered as adjunctive therapy in some cases of psychotropic-induced hyperprolactinemia." (PMID 33768297, 2021). "Patients with hyperprolactinemia were younger (p=0.006) and more likely to be females (p=0.001), had larger and more invasive pituitary adenomas (p<0.001), and had higher levels of GH (p=0.004) and GH nadir (p=0.003), compared to patients with normal prolactin." (PMID 35154007, 2021). "Interestingly, schizophrenic patients with hyperprolactinemia have been reported to have increased pituitary volumes, consistent with the stress-prolactin-dopamine hypothesis." (PMID 34512411, 2021). "The application of a monomeric prolactin reference interval for the 25 % PEG 6000 precipitation procedure allowed for the detection of two cohorts of patients: one with true hyperprolactinemia and the other in whom hyperprolactinemia could be accounted for entirely by macroprolactin." (PMID 34620143, 2021).
hyperprolactinemia (continued). "Moreover, in subjects with hyperprolactinemia, we found only modest elevations in a majority, suggesting that elevated prolactin was likely due to stalk infiltration and reduced dopaminergic signaling rather than a pathologic pituitary process such as a prolactinoma." (PMID 34439280, 2021). "While hyperprolactinemia has long been associated with PES and considered one of the highly prevalent endocrine abnormality, our study also showed consistent results with high prolactin levels among men and women with a slight predisposition towards men though not significant." (PMID 32943019, 2020). "Previous studies have reported on the hyperprolactinemia potential of antipsychotics; however, currently, there is very little head-to-head comparison evidence of antipsychotics to establish the relative differences in serum prolactin levels with antipsychotic treatments in pediatric populations." (PMID 29805808, 2018). "However, during follow-up, hyperprolactinemia may develop in macroprolactinemic subjects who were initially normoprolactinemic along with an increase in anti-PRL autoantibody titers." (PMID 29768629, 2018). "However, there are individuals who, despite increased macroprolactin, also present with high levels of monomeric PRL, leading to “true” hyperprolactinemia with clinical symptoms and the need foran etiologic diagnosis for the proper management of hyperprolactinemia." (PMID 29768629, 2018). "Hyperprolactinemia related to macroprolactin may be due to its lower renal clearance, longer half-life and lower capability to activate hypothalamic dopaminergic tone, which negatively regulates the secretion of pituitary prolactin." (PMID 29768629, 2018). "Thus, the uncertainty of evidence on the long-term risk of hyperprolactinemia is not a reason for dismissing the recommendation for regular monitoring of serum prolactin." (PMID 29889543, 2018). "However, some scholars said that although the PGD can improve the symptoms of hyperprolactinemia caused by antipsychotics, the level of PRL did not change significantly." (PMID 29317896, 2017). "In addition, studies have been shown that presence of macroprolactin may lead to false higher PRL values leading to errors in clinical decision makings and it is suggested that patients with hyperprolactinemia should be tested for macroprolactin as well." (PMID 28593164, 2017). "However, in our opinion, given the uncertainties about the effect of a prolonged, albeit asymptomatic, hyperprolactinemia during development, a baseline PRL, a monthly clinical monitoring of PRL-related symptoms, and periodic PRL assessments (twice per year) are warranted." (PMID 27209326, 2016). "Similar to PRL-producing adenomas, sellar tumors also may exhibit hyperprolactinemia." (PMID 26228535, 2015). "Given its unique activity profile, aripiprazole could potentially normalize elevated prolactin levels induced by other antipsychotics and some studies have shown that adjunctive aripiprazole treatment can indeed reverse hyperprolactinemia induced by other antipsychotics." (PMID 26448615, 2015). "Therefore, the aim of this study was to assess whether metformin administered to bromocriptine-treated patients with hyperprolactinaemia and impaired glucose tolerance affects plasma prolactin levels." (PMID 25239203, 2015). "If these results are replicated in further studies, hyperprolactinaemia may be considered as a potential contributor to cognitive deterioration in psychotic subjects and strategies targeting reduction of prolactin levels may improve cognition in this population." (PMID 24586772, 2014). "Hyperprolactinemia with PRL-secreting adenomas may have some effect on tumor vasculature." (PMID 25431591, 2014).
hyperprolactinemia (continued). "For instance, the brief mean duration for PDSS events is indicative of the transient nature of this event, and the brief mean duration for hyperprolactinemia is indicative of the finding that elevations in prolactin during treatment with olanzapine LAI may be transient in some patients as well." (PMID 24996038, 2014). "Comparatively, mean prolactin concentration in the Bromocriptine group was significantly reduced from 885 mIU/l (±178) to 473 mIU/l (±266) (p < 0.001) demonstrating that both treatments were effective treatment for women with hyperprolactinaemia (normal reference range 25-628 mIU/l)." (PMID 25524718, 2014). "We showed that acute hyperprolactinemia induced in ovariectomized rats using PRL injection or dopamine antagonist treatment rapidly increased apoptosis and decreased proliferation specifically of PRL producing cells (lactotropes), suggesting a direct regulation of these cell responses by PRL." (PMID 24859278, 2014). "In the light of the recent findings and as might be suggested by the present paper, monitoring of plasma prolactin levels and increased risk for VTE due to hyperprolactinemia should also be kept in mind by clinicians, as a more acute and potentially fatal adverse event of antidopaminergic agents." (PMID 23533901, 2013). "In addition, high levels of prolactin may result from pathological conditions such as e.g. pituitary hyperfunction, polycystic ovary syndrome and iatrogenic hyperprolactinemia." (PMID 22606260, 2012). "However, clinical observations of the relationship between PTH and prolactin levels are conflicting, and processes in vivo such as e.g. tumour induced hyperprolactinemia, pregnancy, the menstrual cycle and polycystic ovary syndrome have proved too complex to establish a consensus model of causality." (PMID 22606260, 2012). "Compared to no treatment, dopamine agonists significantly reduced prolactin level (weighted mean difference, -45; 95% confidence interval, -77 to −11) and the likelihood of persistent hyperprolactinemia (relative risk, 0.90; 95% confidence interval, 0.81 to 0.99)." (PMID 22828169, 2012). "In this case, conventional treatment for hyperprolactinaemia would only be symptomatic, given that the underlying cause was not due to a prolactin-secreting tumour, but to the increased vascularity of the bones and associated deformity surrounding the pituitary gland, along with stalk dysfunction." (PMID 18638386, 2008). "Our study demonstrated that metoclopramide (as dopaminergic antagonist) has a very high capacity to induce hyperprolactinemia in rat, indeed the tumour growth accelerated during the observation period and this effect could be influenced or stimulated by PRL release." (PMID 18045456, 2007). "However, there have been reports of bilateral MBC accompanied by hyperprolactinemia, and in this light we cannot exclude the possibility that PRL may indeed be somehow involved." (PMID 17543123, 2007). "Although only one patient reported an adverse event associated with hyperprolactinemia, this adverse event could not be rejected since in this study prolactin levels were not regularly measured." (PMID 15869707, 2005). "Moreover, the lack of significant association between prolactin levels and anemia may be influenced by the severity and duration of hyperprolactinemia, which were not assessed in our cross-sectional design." (PMID 40535391, 2025). "Firstly, positive correlations between cabergoline action on sexual function and on prolactin levels and between the decrease in this hormone and baseline prolactin levels suggest that the improvement in female sexual response may be greatest in women with severe hyperprolactinemia." (PMID 40507082, 2025). "In the 8 men who experienced recurrence of hyperprolactinemia after discontinuation of cabergoline, prolactin reached a median level of 43 ng/ml (IQR 33.8–83.0), corresponding to 70% of prolactin levels at diagnosis." (PMID 40199840, 2025).
hyperprolactinemia (continued). "Clinically, bromocriptine (a dopamine D2 receptor agonist) serves dual therapeutic roles: as first-line management for hyperprolactinemia and as an immunomodulatory adjunct in GLM through PRL suppression." (PMID 40948778, 2025). "Peripheral prolactin levels documented before IPSS were available for 17 out of 19 patients and excluded a state of hyperprolactinemia in all but one patient." (PMID 40765079, 2025). "In a metoclopramide (MCP)-induced hyperprolactinemia mouse model, CPE decreased serum prolactin, PGE2, and inflammatory cytokines, while increasing PGE1 and FSH levels." (PMID 41211554, 2025). "Therefore, an increase in dopamine through the tuberoinfundibular pathway mediated by hyperprolactinaemia could also trigger psychotic symptoms, enhancing the hypothesis that prolactin could be one among many causes and not a side effect of psychosis." (PMID 40896214, 2025). "Thus, managing prolactin side effects may involve sex-specific considerations (e.g., ensuring premenopausal women maintain regular menses and bone health, and monitoring testosterone levels in men with long-term hyperprolactinemia)." (PMID 40589655, 2025). "The elevation in prolactin level appears to be directly related to TSH levels, which should always be measured as part of the differential diagnosis for hyperprolactinemia." (PMID 38578472, 2024). "In patients with hyperprolactinemia, changes in BMD can be induced indirectly by the inhibition of the GnRH–gonadal axis due to increased prolactin levels or by the direct action of prolactin on osteoblasts and, possibly, osteoclast cells." (PMID 38338751, 2024). "We then examined the inhibitory effects of HY7801 on prolactin and pro-inflammatory cytokines in a mouse model of metoclopramide (MCP)-induced hyperprolactinemia." (PMID 39599674, 2024). "One small study about the course of PRL in prediabetic patients with polycystic ovary syndrome (PCOS) and hyperprolactinemia showed that metformin led to an improvement in insulin resistance, which was not accompanied by a decrease in PRL." (PMID 39857650, 2024). "Hypogonadism, a major endocrine complication of hyperprolactinemia that usually resolves or at least improves after successful treatment, might play a significant role in the observed metabolic abnormalities and their improvements after successful treatment in patients with PRL." (PMID 38645431, 2024). "Although (following the Rotterdam criteria) hyperprolactinaemia (HPRL) is an exclusion criterion for PCOS diagnosis, in our interactome, HIF1A has been included in the prolactin pathway." (PMID 39457593, 2024). "Increased TRH production stimulates both thyrotrophic and lactotrophic pituitary cells, resulting in pituitary enlargement and hyperprolactinemia (due to the cross-sensitivity between TSH and prolactin-producing pituitary cells to TRH stimulation)." (PMID 39015673, 2024). "Since hyperprolactinemia is a possible etiological factor in IGM, prolactin-suppressing medications are discussed as potential therapeutic agents." (PMID 39410007, 2024). "Hyperprolactinemia (hyperPRL) is the most common pituitary disorder, with a prevalence ranging from 0.4% in an unselected normal adult population to 9-17% in women with reproductive disorders and it is due to an increase in circulating prolactin (PRL) values, regardless of the underlying cause." (PMID 38194218, 2024). "Because hyperprolactinemia is a possible etiological factor in developing IGM by overstimulating breast parenchymal tissue, medications that lower prolactin levels have been proposed as potential therapeutic agents." (PMID 38304866, 2024). "Therefore, this highlighted the importance of exploring interactions between PRL and the secretion of steroid hormones, which may provide new perspectives on the molecular mechanism of high dose PRL affecting ewe reproduction and the pathology of the development of hyperprolactinemia." (PMID 38665071, 2024).